GSPT1 (G1 to S phase transition 1)
Description:
GTPase component of the eRF1-eRF3-GTP ternary complex, a ternary complex that mediates translation termination in response to the termination codons UAA, UAG and UGA. GSPT1/ERF3A mediates ETF1/ERF1 delivery to stop codons: The eRF1-eRF3-GTP complex binds to a stop codon in the ribosomal A-site. GTP hydrolysis by GSPT1/ERF3A induces a conformational change that leads to its dissociation, permitting ETF1/ERF1 to accommodate fully in the A-site. Component of the transient SURF complex which recruits UPF1 to stalled ribosomes in the context of nonsense-mediated decay (NMD) of mRNAs containing premature stop codons. Required for SHFL-mediated translation termination which inhibits programmed ribosomal frameshifting (-1PRF) of mRNA from viruses and cellular genes.
Synonyms: eRF3a; GST1; ETF3A; 551G9.2
Tractability: Small molecule: a structure with a bound ligand is known; a high-quality ligand is known. PROTAC: it is named in the literature on targeted protein degradation; ubiquitination databases record sites on it; its protein half-life has been measured; a small molecule that binds it is known.
Chemical probes: Eragidomide (high quality), MG-277 (high quality)
Gene: Protein-coding gene on chromosome 16 (11,868,128 to 11,916,082, reverse strand). Ensembl gene ENSG00000103342.
Subcellular location (Human Protein Atlas): Cytosol; Vesicles
Pathways (Reactome):
Metabolism of RNA: Nonsense Mediated Decay (NMD) enhanced by the Exon Junction Complex (EJC); Nonsense Mediated Decay (NMD) independent of the Exon Junction Complex (EJC)
Developmental Biology: Regulation of expression of SLITs and ROBOs
Metabolism of proteins: Eukaryotic Translation Termination
Gene Ontology:
Molecular function: GTPase activity; protein binding; RNA binding; translation release factor activity; GTP binding
Biological process: protein methylation; regulation of translational termination; translational termination; G1/S transition of mitotic cell cycle; nuclear-transcribed mRNA catabolic process, nonsense-mediated decay; translation
Cellular component: cytosolic ribosome; translation release factor complex; cytoplasm; cytosol
Genetic constraint (gnomAD): Loss-of-function variants: 2 observed, 23.33 expected, observed/expected ratio (o/e) 0.0857, 90% interval 0.034 to 0.27. The synonymous counts are far from expectation, so gnomAD's model fits this gene poorly and the ratio says little. Missense variants: 396 observed, 438.21 expected, observed/expected ratio (o/e) 0.9, 90% interval 0.83 to 0.98. Synonymous variants: 224 observed, 169.16 expected, observed/expected ratio (o/e) 1.32, 90% interval 1.19 to 1.48.
Homologues: Orthologues: macaque GSPT1 (99% identical), pig GSPT1 (97% identical), mouse Gspt1 (95% identical), rat Gspt1 (95% identical), dog GSPT1 (95% identical), rabbit GSPT1 (94% identical), guinea pig GSPT1 (84% identical), tropical clawed frog gspt1 (81% identical), chimpanzee GSPT1 (80% identical), zebrafish gspt1l (74% identical), zebrafish gspt1 (73% identical), Drosophila melanogaster mEFTu2 (16% identical), and 3 more. Paralogues in human: GSPT2 (86% identical), EEF1A1 (26% identical), EEF1A2 (25% identical), EIF5B (24% identical), HBS1L (23% identical), TUFM (17% identical), GTPBP1 (17% identical), GTPBP2 (16% identical), MTIF2 (15% identical), EIF2S3 (14% identical), EIF2S3B (14% identical), EFTUD2 (14% identical), and 6 more.
Diseases named in the same sentence as GSPT1 in open-access papers:
GSPT1 is named in the same sentence as 55 diseases in open-access papers, as found by Europe PMC text mining. Sharing a sentence is not in itself a finding about the gene and the disease. The quoted sentences say what the papers report.
acute myeloid leukemia (14 papers, 2021 to 2025). Acute myeloid leukemia (AML) is a group of neoplasms arising from precursor cells committed to the myeloid cell-line differentiation. "Current research on ZHX-161 is exploringthe opportunities for therapeutically targeting GSPT1, consideringthat GSPT1 degradation has already shown significant potential inthe treatment of acute myeloid leukemia." (PMID 35856839, 2023). "Drugs that degrade GSPT1 via the CRL4CRBN ubiquitin ligase are a new class of cancer therapy in active clinical development with evidence of activity against acute myeloid leukemia in early-phase trials." (PMID 35763353, 2022). "Additionally, CC-90009 has entered clinical trials for the treatment of patients with acute myeloid leukaemia, which lays the groundwork for the application of GSPT1-deletion-based strategies in treating viral infections." (PMID 41471039, 2025). "The first-in-class GSPT1 degrader CC-885 demonstrated cytotoxicity across multiple cell lines derived from different tumor types, as well as efficacy against primary samples from patients with acute myeloid leukemia (AML) with relative sparing of lymphocytes." (PMID 35763353, 2022). "Degradation of GSPT1 is detrimental in acute myeloid leukemia (AML) cell lines and patient-derived AML samples." (PMID 34834536, 2021). "Accordingly, GSPT1-selective immunomodulatory drugs, such as CC-90009, MRT-2359, and SJ6986, have been developed, and CC-90009 and MRT-2359 are currently being explored in clinical trials involving patients with acute myeloid leukemia and lung cancer, respectively." (PMID 39117611, 2024).
gastric cancer (11 papers, 2009 to 2025). A primary or metastatic malignant neoplasm involving the stomach. "For example, circGSPT1, which is lowly expressed in gastric cancer, can encode GSPT1‐238aa protein, and the GSPase domain of GSPT1‐238aa protein can interact with the PI3K/Akt/mTOR signalling pathway." (PMID 38506082, 2024). "It has been reported that GSPT1 is negatively regulated by miR-27b-3p via combining with the 3′-untranslated region and that patients with gastric cancers and lower miR-27b-3p expression demonstrate a poorer prognosis." (PMID 39117611, 2024). "In summary, hsa_circ_0001944 sponges miR‐498 and furtherly regulates the expression of GSPT1 in gastric cancer cells." (PMID 36597856, 2023). "The present study demonstrates the circFIRRE/miR‐498/GSPT1 axis contributes to gastric cancer development." (PMID 36597856, 2023). "Meanwhile, we confirmed that hsa_circ_0001944 sponged miR‐498 and subsequently regulated GSPT1 expression in gastric cancer cells." (PMID 36597856, 2023). "Actually, GSPT1 has been reported as promoting gastric cancer cell proliferation, invasion, and migration." (PMID 36597856, 2023). "The bioinformatic analysis, qPCR, Western blotting, and immunohistochemistry were fulfilled to detect the expression of hsa_circ_0001944, miR‐498, and GSPT1 in gastric cancer." (PMID 36597856, 2023). "By inhibiting miRNA-144, GSPT1 over-expression can promote the proliferation, invasion, and migration of gastric cancer cells, thereby promoting gastric cancer progression, which is consistent with the role of GSPT1 in tumors." (PMID 33819920, 2021). "In gastric cancer tissues, GSPT1 is highly expressed, miRNA-144 expression is down-regulated, and GSPT1 expression is significantly increased." (PMID 33819920, 2021). "GSPT1 expression level was markedly increased in gastric cancer 31, colorectal cancer 32, and so on." (PMID 32127947, 2020). "G1 to S phase transition 1 (GSPT1) has been demonstrated oncogenic activity in gastric cancer." (PMID 36597856, 2023). "Therefore, our research demonstrated that hsa_circ_0001944 enhanced GSPT1 expression via sponging miR‐498 to promote gastric cancer cell proliferation and invasion." (PMID 36597856, 2023). "Moreover, circFIRRE sponged miR‐498 to increase GSPT1 expression, thereby promoted the malignant phenotype of gastric cancer." (PMID 36597856, 2023). "The current research demonstrates the circFIRRE/miR‐498/GSPT1 axis contributes to gastric cancer development, which may offer a target for gastric cancer therapy and potential prognostic biomarker." (PMID 36597856, 2023). "GSPT1 was the targeted gene of miR‐144 or miR‐27b‐3p in gastric cancer." (PMID 36597856, 2023). "Hsa_circ_0001944 could regulate the expression of GSPT1 via miR‐498 sponging in gastric cancer." (PMID 36597856, 2023). "Therefore, our study found that the hsa_circ_0001944/miR‐498/GSPT1 axis can regulate the development of gastric cancer and may also give a hidden target for gastric cancer treatment." (PMID 36597856, 2023). "Previous studies of gastric cancers have found that genes such as BUB1, eRF3/GSPT1, and hCG-1 were correlated with histological type." (PMID 19337254, 2009). "Among the 19 uniquely identified genes, 7 (GSPT1, TFF3, KLF4, ITK, GNB2L1, FLI1, and GNG5) were not included in the KEGG gastric cancer pathway, indicating that they have not been previously recognized as canonical GAC-related genes." (PMID 41284725, 2025).
colon cancer (9 papers, 2018 to 2025). "Bioinformatics analysis has shown that GSPT1 is dysregulated in colon cancer and is associated with tumor progression." (PMID 33819920, 2021). "GSPT1 protein was upregulated in colon cancer, and GSPT1 expression positively correlated with tumor size." (PMID 39117611, 2024). "For example, MINCR aggravates colon cancer and glioma via the miR-708-5p-mediated Wnt/β-catenin pathway and miR-876-5p/GSPT1 axis, respectively." (PMID 36741910, 2023). "In the present study, cell biology, pathology, and molecular biology technology are used to clarify the biological function of GSPT1 in colon cancer." (PMID 33819920, 2021). "Taken together, our findings suggest that the GSPT1/GSK pathway exerts tumor-promoting actions in colon cancer oncogenesis and progression." (PMID 33819920, 2021). "In the present study, we analyzed the sequencing data of colon cancer in the TCGA database and found that GSPT1 was abnormally highly expressed in colon cancer tissue and related to tumor size." (PMID 33819920, 2021). "After GSPT1 was silenced in HCT116 colon cancer cells, the expression of CyclinD1, CDK4/6, cyclinE, CDK2, p21, and p27 was detected by Western blot." (PMID 33819920, 2021). "In the present study, we found that GSPT1 negatively regulated the GSK-3β signaling pathway in colon cancer cells." (PMID 33819920, 2021). "In general, aberrant GSPT1 expression in colon cancer suggests that GSPT1 is strongly correlated with colon cancer tumorigenesis and progression." (PMID 33819920, 2021). "Among colon cancer patients, the expression level of GSPT1 gradually increased from stage I to II to III cancer, and decreased slightly in stage IV." (PMID 33819920, 2021). "Compared with the empty vector group, the number and size of cell clone formation of HCT116 cells were significantly increased after GSPT1 over-expression (P<0.01), which confirmed that GSPT1 promotes the proliferation of colon cancer." (PMID 33819920, 2021). "Depletion of GSPT1 suppressed cell proliferation, migration, and invasion-induced colon cancer cell apoptosis in vitro and restrained tumorigenicity in vivo in HCT116 colon cancer cells." (PMID 33819920, 2021). "The in vivo tumorigenesis experiment with nude mice confirmed that the proliferation and tumorigenicity of colon cancer cells were significantly inhibited after GSPT1 silencing." (PMID 33819920, 2021). "We also analyzed the biological function of GSPT1 in colon cancer and the related molecular biological mechanism." (PMID 33819920, 2021). "First, we silenced the expression of GSPT1 in colon cancer cell lines HCT116 and SW480 by RNA interference." (PMID 33819920, 2021). "Compared to the control group, the tumors formed by GSPT1-knockdown colon cancer cells grew more slowly and were significantly smaller and lighter." (PMID 33819920, 2021). "The expression level of GSPT1 mRNA was assessed by quantitative P in 25 cases of colon cancer and corresponding adjacent tissues." (PMID 33819920, 2021). "The effect of GSPT1 interference on the colony formation ability of colon cancer cells was assessed using the plate clone formation test." (PMID 33819920, 2021). "Compared with normal colon, the expression level of GSPT1 was significantly increased in colon cancer tissues." (PMID 33819920, 2021). "More recently, GSPT1 was delineated as a tumor-promoting factor in several types of cancers, such as astrocytoma, liver cancer, gastrointestinal cancer, lung cancer, and colon cancer." (PMID 39117611, 2024). "The result showed that the percentage of apoptotic cells in the control group (4.26±1.93%) and si-NC group (4.04±1.50%) were both significantly lower than that in the si-GSPT1 group (20.16±2.42%) (P<0.001), suggesting that down-regulation of GSPT1 induced colon cancer cell apoptosis." (PMID 33819920, 2021). "GSPT1 plays an important role in the genesis, progression, and prognosis of colon cancer." (PMID 33819920, 2021).
colon cancer (continued). "The GSPT1/GSK pathway exerts tumor-promoting actions in colon cancer oncogenesis and progression." (PMID 34150649, 2021). "The role of GSPT1 in advanced colon cancer was also investigated." (PMID 33819920, 2021). "GSPT1 was significantly up-regulated in colon cancer tissues and cell lines." (PMID 33819920, 2021). "The effect of GSPT1 expression on cell apoptosis in human colon cancer cells was also investigated." (PMID 33819920, 2021). "The results showed that the expression of GSPT1 was significantly higher in colon cancer patients." (PMID 33819920, 2021). "The GSPT1/GSK pathway may thus be an effective target for controlling colon cancer." (PMID 33819920, 2021). "However, the biological function and molecular mechanism of GSPT1 in colon cancer remain unclear." (PMID 33819920, 2021). "In order to investigate the relationship between GSPT1 and GSK-3β in colon cancer cells, the expression of GSK-3β was up-regulated after GSPT1 was silenced in HCT116 cells." (PMID 33819920, 2021). "Here, we identified the binding relationship between GSPT1 protein and E3 ubiquitin protein ligase (TRIM4) in colon cancer cells." (PMID 33819920, 2021). "The results of the transwell Matrigel experiment showed that the number of cells passing through the transwell basement membrane decreased significantly after GSPT1 was silenced by HCT116 and SW480, indicating that the invasion ability of colon cancer cells interfered with GSPT1 was inhibited." (PMID 33819920, 2021). "After GSPT1 was silenced, the expression of GSK-3β, p21, and p27 increased, and the expression of CyclinD1, CDK4/6, cyclinE, and CDK2 decreased; these changes affected the progression of colon cancer cells from G1 phase to S phase and blocked the cell cycle." (PMID 33819920, 2021). "Taken together, these results suggest that GSPT1 regulates CyclinD1, CDK4, and Cdk6 through GSK-3 β, and indirectly affects the expression of cyclinE and CDK2 through p21 and p27, thus regulating the transformation of colon cancer cells from the G1 phase to S phase and promoting tumor progression." (PMID 33819920, 2021).
breast carcinoma (6 papers, 2013 to 2025). "The aim of this study was to evaluate a novel molecular glue, dubbed GT19630, which degrades both MYC and GSPT1, for the treatment of breast cancer." (PMID 39875774, 2025). "Additional studies are needed to better understand the role of GSPT1 and its potential interaction with other clinical parameters in cardiotoxicity of breast cancer treatment, especially in patients treated with RT." (PMID 33425072, 2020). "A previous study has also tested from women with palpable lesions suspicious of breast cancer for aberrant promoter hypermethylation, and the GSPT1 candidate gene can be easily detected in fine needle aspirated washings." (PMID 24565108, 2013). "The aim of this study was to investigate a novel molecular glue that degrades MYC and GSPT1 known as GT19630, as a potential new treatment for breast cancer." (PMID 39875774, 2025). "In this study, by integrating CRISPR-CAS9 functional genomics (DEPMAP database) and TCGA multi-omics data, seven key genes (CDK7, CLTC, COPB2, CRNKL1, GSPT1, NSF and PSMD12) that are closely related to the proliferation and prognosis of breast cancer were systematically identified." (PMID 40657358, 2025).
colorectal cancer (5 papers, 2018 to 2026). A primary or metastatic malignant neoplasm that affects the colon or rectum. "Several studies reported that the presence of GSPT1 with a 12 glycine repeat is correlated with increased risks of gastric, breast, and colorectal cancers." (PMID 30696065, 2019). "MiR-144 was markedly down-regulated in colorectal cancer cells and suppressed the expression of GSPT1 to regulate the cell proliferation-related gene expressions of c-myc, survivin and Bcl2L15 and metastasis-related factor MMP28." (PMID 30126852, 2018). "We also show that the weak degradation of GSPT1 by CC-885correlates with a modest cell growth inhibition in HCT116 (IC50 =0.198 μM), highlighting that morepotent GSPT degraders could be used in colorectal cancer." (PMID 35848491, 2022).
hemophilia (5 papers, 2018 to 2023). Hemophilia is a genetic disorder characterized by spontaneous hemorrhage or prolonged bleeding due to factor VIII or IX deficiency. "ASOs targeting Gspt1 have previously been shown to promote PTC readthrough by G418 in a hemophilia mouse model." (PMID 33764477, 2021). "However, ASO-mediated depletion of Gspt1 in another study using a hemophilia mouse model with nonsense mutations was only associated with minor reduction in eRF1 levels." (PMID 33764477, 2021). "Interestingly, when combining all three treatments together (Upf3b-GalNAc-ASO/Gspt1-GalNAc ASO/geneticn), we were able to detect full-length hFIX proteins in female hemophilia mice, while the abundance was < 1% of hFIX-WT mice." (PMID 29334995, 2018). "The amount of hFIX protein detected in male hemophilia mice with either the combination of Upf3b-GalNAc-ASO and Gspt1-GalNAc-ASO, or the combination of Upf3b-GalNAc-ASO and geneticin, although reliably detected, remained lower than the threshold 1% of hFIX-WT abundance." (PMID 29334995, 2018).
glioma (4 papers, 2022 to 2024). A benign or malignant brain and spinal cord tumor that arises from glial cells (astrocytes, oligodendrocytes, ependymal cells). "Taken collectively, these findings indicate that the MINCR/miR-876-5p/GSPT1 axis plays a vital role in glioma development and progression." (PMID 37215074, 2023). "For instance, Li’s experimental research proves that LncRNA MINCR can regulate the miR-876-5p/GSPT1 axis to aggravate the progression of glioma." (PMID 36406128, 2022). "Furthermore, MINCR negatively regulates and sponges miR-876-5p to control GSPT1 expression in glioma tissues and cell lines." (PMID 37215074, 2023).